HLA-G (major histocompatibility complex, class I, G)
Diseases named in the same sentence as HLA-G in open-access papers (continued):
Sharing a sentence is not in itself a finding about the gene and the disease.
gastric cancer (continued). "DC-10s is a subset of tolerogenic DCs which express high levels of HLA-G and secrete IL-10 and IL-6 in peripheral blood of patients with gastric cancer." (PMID 36053326, 2023). "This is, to the best of our knowledge, the first time that an association between the HLA-G 3’UTR region and the development of gastric cancer is disclosed in our population." (PMID 34557189, 2021). "Further studies, focusing on HLA-G expression on the patients, are required to precisely assess the role of HLA-G in gastric cancer." (PMID 34557189, 2021). "Kaplan-Meier plotter was exerted to analyze the prognostic value of the HLA-G gene expression for breast, ovarian, lung, and gastric cancers by combining gene expression and cancer patient survival." (PMID 32867672, 2020). "Lastly, the outcomes obtained from Kaplan Meier bioinformatics analyses indicated that the HLA-G gene deregulation affected the overall survival rate of patients with ovarian, lung and gastric cancer and had the prognostic significance." (PMID 32867672, 2020). "Increased HLA-G expression correlates with immune evasion during colorectal cancer progression and in gastric cancer." (PMID 30899759, 2019). "The use of these disease biomarkers in conjunction with genetic screening for HLA-G*01:01:01 could provide greater robustness in the early prediction of gastric cancer." (PMID 39408976, 2024). "Further elucidation of HLA-G-related pathways could lead to personalized treatment strategies and improved patient outcomes in gastric cancer." (PMID 39549048, 2024). "The expression of HLA-G in exosomes may provide valuable insights into the role of HLA-G and exosomes in the development of gastric cancer." (PMID 37573450, 2023). "Human Leucocyte Antigen‐G (HLA‐G) positive expression in gastric cancer patients indicated a poor prognosis, and its possible mechanism may be that HLA‐G combined with LILRB1 inhibited NK cell proliferation and function." (PMID 36748687, 2023). "HOTAIR might act as competing endogenous RNA and interact with microRNA (miRNA), such as miR-331-3p and miR-152, to regulate human epidermal growth factor receptor 2 (HER2) and human leukocyte antigen-G (HLA-G) expression in gastric cancer cells." (PMID 32509569, 2020). "In this study, HLA-G expression in 523 gastric cancer (GC) lesions and 283 case-matched PTTs was analyzed using immunohistochemistry (IHC), and the clinical significance of HLA-G expression in GC lesions and case-matched PTTs was evaluated." (PMID 41181133, 2025). "However, underlying mechanisms, potential biological roles, and clinical significance of HLA-G expression in mucous neck cells in gastric cancer development remain unknown and require further exploration." (PMID 41181133, 2025). "Finally, although several authors described the effect of HLA-G in the immune system, functional analysis may enlight the actual immunomodulatory properties of this molecule in the context of gastric cancer." (PMID 39549048, 2024). "However, there is currently a lack of study on the association between HLA-G and cancers, with the exception of gastric cancer." (PMID 38577332, 2024). "Expression of HOX transcript antisense intergenic RNA (HOTAIR) correlates positively with HLA-G expression in gastric cancer (GC)." (PMID 31850199, 2019). "In gastric cancer, HOTAIR acts as a ceRNA by sponging miRNA-152, resulting in promoting HLA-G expression." (PMID 36207500, 2022). "Studies in patients with non-small lung carcinoma (NSCLC), gastric cancer, and CRC reported co-expression of HLA-G and its receptors ILT2 or ILT4 on tumor cells, and showed a correlation between co-expression and poor clinical outcome." (PMID 33213057, 2020). "Co-expression of HLA-G and ILT2 or ILT4 has been observed in CRC, NSCLC and gastric cancer." (PMID 33213057, 2020).
gastric cancer (continued). "In gastric cancer cells, TGF-β induces HLA-G expression through miR-152 inhibition, which results in the suppression of NK cell functions mediated by the interaction between HLA-G and the receptor ILT2." (PMID 31948072, 2020). "The interactions between HLA-G and miR-152 (and TGF-β) have been also analyzed by Guan and colleagues in gastric cancer (GC)." (PMID 27652273, 2016). "Whereas more frequent HLA-G expression was observed in patients with advanced stages of gastric cancer, lymph node involvement, or advanced T-stage, affecting the prognosis of gastric cancer patients, which may be related to the induction of high TNF-α expression by HLA-G." (PMID 37533569, 2023).
glioma (25 papers, 2008 to 2025). A benign or malignant brain and spinal cord tumor that arises from glial cells (astrocytes, oligodendrocytes, ependymal cells). "As it is the first study concerning HLA-G 14bp ins/del polymorphism in gliomas, our study is the second one." (PMID 35626255, 2022). "All these data on pediatric solid tumors underline that HLA-G and other IC molecules expressed on tumor cells and in the tumor microenvironment are actively involved in tumor progression, in particular in gliomas, Ewing sarcoma, and NB." (PMID 35328349, 2022). "In the group of patients with gliomas, we compared the level of sHLA-G with HLA-G 14bp ins/del variants to determine if the investigated polymorphism affects the plasma sHLA-G level." (PMID 35626255, 2022). "As the expression of HLA-G is finely tuned by genetic variations (polymorphisms) in the non-coding region of the locus, besides plasma levels of soluble HLA-G in glioma patients, we also investigated the gene polymorphism of this molecule in glioma patients." (PMID 35626255, 2022). "The HLA-G 14bp ins/del polymorphism and the plasma level of soluble HLA-G (sHLA-G) were investigated by a polymerase chain reaction and ELISA, respectively, in 59 glioma patients." (PMID 35626255, 2022). "The level of serum soluble HLA-G is negatively associated with survival of glioma patients." (PMID 36177003, 2022). "The production of IL- 1β from glioma cells is responsible for the activation of TLR-4 and overexpression of HMGB1, which most likely gives rise to HLA-G, contributing to glioma immune evasion response." (PMID 38698968, 2024). "The other results using the Kaplan–Meier Plotter database showed that patients with higher HLA-G mRNA expression in pancreatic ductal adenocarcinoma and gliomas had significantly shorter DFS." (PMID 39594832, 2024). "We are aware of a limited number of glioma patients and recognize that there are many factors that can affect their survival, in our study, we focused only on HLA-G." (PMID 35626255, 2022). "The expression of HLA-G and its role in cancer progression has been addressed in gliomas, glioblastoma, and Ewing sarcoma, whereas limited information is available on meningioma, retinoblastoma, and other sarcomas." (PMID 35328349, 2022). "Following IFN-γ treatment, the number of gliomas expressing HLA-G mRNA dramatically increased since 10 out of 12 tumor cell lines were then HLA-G positive." (PMID 32922387, 2020). "Increased levels of HLA-G expression, promoter activity, and surface protein expression were detected in glioma cells cultured with the addition of IL-1β." (PMID 28781970, 2017). "These experiments demonstrated that IL-1β induces HLA-G in glioma cells in a HIF-1α-dependent manner." (PMID 28781970, 2017). "We here demonstrate the induction of HLA-G in glioma cells under hypoxia-mimicking conditions and, for the first time, a functional HIF-1 target site." (PMID 27577073, 2016). "We first investigated the effect of hypoxia-mimicking agent desferrioxamine (DFX) treatment on HLA-G expression in U251MG glioma cells." (PMID 27577073, 2016). "Nevertheless, the upregulation of HLA-G and HMGB1, one of the identified TIM-3 ligands, was induced by IL-1β, and HLA-G could further increase HLA-G protein level in dependence on TLR4 in glioma." (PMID 38310272, 2024). "In addition, glioma cells express immunosuppressive cell surface molecules like HLA-G or release soluble immunosuppressive substances like TGF-β to inhibit anti-tumor immune responses and promote cancer progression." (PMID 37602882, 2023). "We analyzed the presence of 14 nt insert in the 3′UTR region of HLA-G and found a significantly higher proportion of glioma patients carrying the 14 nt insert in both homozygous and heterozygous states (14 ins/ins and 14 del/ins) compared to the control group of healthy subjects (p = 0.03)." (PMID 35626255, 2022).
glioma (continued). "In our previous study analyzing HLA-G 5′URR, we found a genetic association of haploblock consisting of −762 T, −716 G, −689 G, −666 T, and −633 A allele followed by −486 C and −201 A alleles with susceptibility to developing gliomas for the first time." (PMID 35626255, 2022). "HLA-G plays a great role in the immunopathogenesis of cancer, and probably also gliomas, and the plasma level of sHLA-G might have an impact on the survival of glioma patients." (PMID 35626255, 2022). "Similarly, the produced HIF-1 silencing diminished HLA-G protein expression in glioma cells (A17, U87MG) after IL-1β induction of HIF-1, even if in normoxia." (PMID 28781970, 2017). "Furthermore, gliomas induce upregulation and expression of HLA-G and HLA-E by GAMs in a majority of glioblastomas, thus hindering anti-glioma activity." (PMID 23983766, 2013). "To determine if the investigated polymorphism affects the plasma level of sHLA-G in glioma patients, we compared the level of sHLA-G in patients with different variants of the HLA-G 14 ins/del genotypes; however, the differences were not statistically significant." (PMID 35626255, 2022). "The authors observed that a glioma tumor cell line that does not express HLA-G, when treated with the hypoxia-mimicking agent desferrioxamine (DFX), expressed high amounts of HLA-G mRNA and protein." (PMID 34884849, 2021). "Both treatments enhanced the amount of HLA-G mRNA and protein in HLA-G negative U251MG glioma cells." (PMID 27577073, 2016). "We also reported that 5-aza- dC demethylating treatment induced HLA-G expression in a cellular model of human glioblastoma, the HLA-G negative U251MG glioma cell line." (PMID 27577073, 2016). "IL- 1β secreted from glioma cells was found to be responsible for the activation of TLR-4 and upregulation of high mobility group box 1 (HMGB1) protein, which eventually results in the increase of HLA-G, a non-classical HLA class I antigen that contributes to glioma immune evasion response." (PMID 34439380, 2021).
renal cell carcinoma (25 papers, 2012 to 2025). "In renal cell carcinoma or choriocarcinoma cells, stronger killing capacity of NK cells against tumor cells was evoked after silencing of HLA-G with the CRISPR/Cas9 system." (PMID 38310272, 2024). "Here, we used CRISPR/Cas9 gene editing to block the HLA-G expression in two tumor cell lines expressing HLA-G, including a renal cell carcinoma (RCC7) and a choriocarcinoma (JEG-3)." (PMID 34773056, 2021). "In conclusion, we believe that HLA-G can serve as a potential prognostic factor as well as therapeutic target in tumors, especially in renal cell carcinoma and thyroid carcinoma." (PMID 34276642, 2021). "This study investigates the interaction between CREB and HLA-G in different renal cell carcinoma (RCC) subtypes and its correlation to clinical parameters." (PMID 32993793, 2020). "Intratumor heterogeneity of HLA-G expression has been firstly detailed in 19 primary renal cell cancer (RCC) tumor tissues." (PMID 33329527, 2020). "For instance, Gene HLA-G has been reported before to reveal its expression, regulation, structure and function in renal cell carcinoma." (PMID 29299153, 2017). "Expression and function of HLA-G and regulatory microRNA (miR-152, -148A, -148B, and -133A) have been analyzed by Jasinski-Bergner and colleagues in renal cell carcinoma (RCC)." (PMID 27652273, 2016). "This review will discuss the expression, regulation, functional and clinical relevance of HLA-G expression in urological tumors as well as its use as a putative biomarker and/or potential therapeutic target for the treatment of renal cell carcinoma as well as urothelial bladder cancer." (PMID 35185904, 2022). "That miR expression may play a role in HLA expression was demonstrated by the group of Seliger, which observed that in renal cell carcinoma, overexpression of specific miRNAs led to a reduction of HLA-G, enhancing NK-cell mediated cytotoxicity in vitro." (PMID 34439175, 2021). "Previous studies revealed that the degree of HLA-G or its receptors ILT2/4 expression varies markedly among different locations in a primary renal cell cancer tumor lesion, indicating the complexity of intratumor heterogeneity of HLA-G and its receptor expression." (PMID 33329527, 2020). "The non-classical human leukocyte antigen G (HLA-G) is expressed at a high frequency in renal cell carcinoma (RCC) and is associated with a higher tumor grade and a poor clinical outcome." (PMID 27057628, 2016). "Under pathophysiologic conditions constitutive HLA-G surface expression was frequently upregulated in hematopoietic and solid tumors including renal cell carcinoma (RCC) which could often be correlated to an unfavorable prognosis and poor clinical outcome of tumor patients." (PMID 27057628, 2016). "A recent study focused on tumor-infiltrating CD8+ T cells that express the HLA-G receptor ILT2 in renal-cell carcinoma (RCC), and the results emphasize the potential of therapeutically targeting the HLA-G/ILT2 checkpoint in HLA-G+ tumors." (PMID 32670296, 2020). "In BRAFV600E+ papillary thyroid cancer, HLA-G, CTLA-4, and PD-L1 expression were consistently high and significantly inversely correlated with thyroid differentiation score, coinciding with the data in renal cell carcinoma." (PMID 38310272, 2024). "Other studies also reported that HLA-G expression in tumor cell lines such as ovarian carcinoma, hepatocellular carcinoma (HCC), glioma, and renal cell carcinoma could be protective against NK cytolysis." (PMID 30319626, 2018). "Collectively, these data demonstrated that the function of HLA-G/ILT2 and PD-1/PD-L1 checkpoint in renal cell carcinoma is dicotomic, and HLA-G+/PD-L1+ tumor cells may abrogate the function of two distinct cytotoxic effector cell subsets in the tumor microenvironment." (PMID 35328349, 2022).
COVID-19 (20 papers, 2020 to 2025). A disease caused by infection with severe acute respiratory syndrome coronavirus 2. "Its relevance in COVID-19 has been previously reported, as we observed the association of the HLA-G 14-bp indel variant with the requirement of IMV." (PMID 39081501, 2024). "Of these genes, there is research to identify HLA-G as being associated with COVID-19, however, the rest of these molecules appear to be novel." (PMID 37308820, 2023). "The association between HLA-G expression and COVID-19 severity and progression has been studied in some studies with contradictory results." (PMID 37342325, 2023). "Non-classical HLA class I molecules with tolerogenic activity, such as HLA-G and HLA-E, have also been associated with COVID-19." (PMID 35062298, 2022). "On the other hand, some drugs used for COVID-19 treatment, such as corticosteroids, have been associated with the modulation of HLA-G expression." (PMID 36077133, 2022). "Moreover, the study delved into the immunomodulatory function of HLA-G and its interaction with HLA-E, revealing significant associations with COVID-19 severity." (PMID 40391199, 2025). "As NKG2A expression is highly associated with the severity of COVID-19, these findings indicate that the genetic variation of HLA-G could be linked to susceptibility to disease and host immune response regulation during SARS-CoV-2 infection." (PMID 34938296, 2021). "Overexpression of HLA-G in viral infections such as COVID-19 facilitates the spread of infection by inhibiting the proliferation of T and B lymphocytes, the activity of antigen-presenting cells (APCs), and CD8+ cytotoxicity." (PMID 40391199, 2025). "The marginal association with the length of IMV days and hospitalisation stay suggests a relevant role of HLA-G in pulmonary function, as it was also observed in the desaturation after 6MWT in post-COVID-19 patients." (PMID 39081501, 2024). "This is the first evaluation of the HLA-G 14-bp indel (rs371194629) in the follow-up of patients with post-COVID-19 condition." (PMID 39081501, 2024). "Higher plasma levels of the soluble form of HLA-G (sHLA-G) have been found in patients with COVID-19 compared to uninfected control subjects; the levels increased in patients with severe disease but decreased in critical patients." (PMID 39081501, 2024). "This study aimed to confirm the robustness of previous findings with a new pool of individuals and investigate the role of HLA-G in COVID-19." (PMID 37342325, 2023). "Haplotype frequencies observed at the HLA-G 3’UTR polymorphic sites in COVID-19 patients divided according to severity of the clinical manifestations." (PMID 37342325, 2023). "Among these, recent studies have explored the role of HLA-G molecules and their immunomodulatory effects in COVID-19, but there are very few reports exploring the genetic basis of these manifestations." (PMID 37342325, 2023). "Disease progression and its complications seem to be related to a high expression of HLA-G on the surface of infected cells, whereas a reduction in HLA-G expression in immune cells, such as T cells, B cells, and monocytes, was observed in COVID-19 patients." (PMID 35062298, 2022). "We evaluated the plasma soluble HLA-G (sHLA-G) in 239 individuals, arranged in COVID-19 patients (n = 189) followed up at home or in a hospital, and in healthy controls (n = 50)." (PMID 36077133, 2022). "A high expression of HLA-G in the cell membrane was reported in the early inflammation stage in Chinese patients with COVID-19." (PMID 35062298, 2022). "In an early case report from a recovering COVID-19 patient, a high-low-high HLA-G variation in lymphocyte and monocyte population with stable levels of CD158d was described." (PMID 35625671, 2022). "In a patient recovered from COVID-19 for four weeks, induced HLA-G expression was observed in the intestinal mucosa epithelial cells and lymphocytes at the sites corresponding to SARS-CoV-2 positivity." (PMID 34938296, 2021).